CAV1 (caveolin 1)
Diseases named in the same sentence as CAV1 in open-access papers (continued):
Sharing a sentence is not in itself a finding about the gene and the disease.
benign breast diseases (1 paper, 2007). "In myoepithelial cells of ducts and lobuli as well as in blood vessels, expression of Caveolin-1 was consistently found in normal breast tissue as well as both benign breast diseases and DCIS." (PMID 17915016, 2007). "No Caveolin-1 expression was observed in epithelial cells of normal breast tissue (n = 5), benign breast disease (n = 295) and DCIS (n = 108)." (PMID 17915016, 2007). "In contrast, when evaluating 108 cases of DCIS specimens, 236 cases of benign breast disease and five cases of healthy breast tissue, no Caveolin-1 expression could be found in the epithelial component." (PMID 17915016, 2007).
bladder tumor (1 paper, 2022). "The expression levels of a portion of feature genes, such as ANGPTL2, CAV1, FNBP1, FXD6, MAP1A, and ZCCHC24 were significantly decreased in bladder tumor cell lines." (PMID 35719407, 2022).
bone sarcoma (1 paper, 2011). A sarcoma that arises from the bone. "This review is focused on the role of caveolin-1 in several soft tissue and bone sarcomas and discusses the use of this protein as a potential diagnostic and prognostic marker and as a therapeutic target." (PMID 21471610, 2011).
brain glioma (1 paper, 2017). A malignant glioma that involves the brain. "In a rat brain glioma (C6) model, expression of Cav-1 protein at tumor sites was greatly increased after intracarotid infusion of minoxidil sulfate, which is a selective adenosine 5’-triphosphate-sensitive potassium channel (K (ATP) channel) activator." (PMID 29221162, 2017).
cardioembolic stroke (1 paper, 2019). "CAV1, SURF1, PLEKHH2, ECD, BNIP1, CAV2 are found to be associated with cardioembolic stroke and Small vessel stroke in Europeans." (PMID 32038707, 2019).
cavernous hemangioma (1 paper, 2013). A hemangioma characterized by the presence of cavernous vascular spaces. "Immunostaining for caveolin-1 showed decreased or no caveolin-1 reactivity in the hyalinized lesions of the sclerosed hemangioma, but abundant caveolin-1 reactivity in the residual cavernous hemangioma." (PMID 23714181, 2013).
cerebral malaria (1 paper, 2020). A sequestration of Plasmodium falciparum in the brain, which can cause coma and/or seizures. "This miR-Ago2 could down-regulate the expression of CAV-1 and ATF2 resulting in endothelial cells alteration which is a plausible factor contributing vascular dysfunction in cerebral malaria." (PMID 32778117, 2020).
cerebrovascular disease (1 paper, 2022). "Besides MMD, serum level of Cav-1 has been reported in other cerebrovascular disease." (PMID 35557625, 2022).
childhood asthma (1 paper, 2021). "In our study, CAV1 participated in focal adhesion, thus contributing to the pathogenesis of childhood asthma." (PMID 34456632, 2021).
cholangiocarcinoma (1 paper, 2025). A carcinoma that arises from the intrahepatic biliary tree (intrahepatic cholangiocarcinoma) or from the junction, or adjacent to the junction, of the right and left hepatic ducts (hilar cholangiocarcinoma). "This suggests that downregulation of CAV1 in cholangiocarcinoma cells can significantly inhibit their growth and proliferation." (PMID 40304434, 2025). "In summary, downregulation of CAV1 expression in cholangiocarcinoma cells can significantly inhibit their proliferation, migration, and invasion abilities." (PMID 40304434, 2025). "We assessed the colony formation ability of cholangiocarcinoma cells after knocking down CAV1 and found a significant reduction in the number of colonies in the si‐CAV1 group compared to the si‐NC group." (PMID 40304434, 2025). "Additionally, immunohistochemistry staining images from the Human Protein Atlas (HPA) database showed higher expression levels of CAV1 in cholangiocarcinoma tissues compared to normal tissues." (PMID 40304434, 2025). "Therefore, we first verified the differential expression levels of CAV1 in cholangiocarcinoma‐related cell lines, which showed varying degrees of elevated expression in cholangiocarcinoma cell lines, with the highest expression level in HUCCT1." (PMID 40304434, 2025). "Although previous studies have indicated the importance of CAV1 in the development and progression of cancers in organs such as the colon and breast, its expression and role in cholangiocarcinoma have not been thoroughly explored." (PMID 40304434, 2025).
Chronic colitis (1 paper, 2015). A chronic inflammatory disease of the large intestine (colon, cecum and rectum). "In chronic colitis, colon Cav-1 levels were significantly and inversely correlated with colon inflammatory scores in (P < 0.0003, r = -0.828), and also inversely correlated with IL-17 and TNF, but not IFN, levels (P < 0.01; r = -0.641 for IL-17; P < 0.02, r = -0.624 for TNF)." (PMID 25756273, 2015). "We found that colonic Cav-1 levels were reduced in mice with TNBS-induced acute (statistical significance was not reached) and statistically significantly reduced in chronic colitis in both Balb/c and C57BL/6J mice." (PMID 25756273, 2015).
chronic gastritis (1 paper, 2013). Inflammation of the stomach that is chronic in nature. "Histopathological analysis revealed that both WT and Cav1-KO mice developed active chronic gastritis accompanied by infiltration of mononuclear and polymorphnuclear (PMN) cells into the gastric mucosa." (PMID 23592983, 2013).
cicatricial alopecia (1 paper, 2021). Scarring hair loss, also known as cicatricial alopecia, is the loss of hair which is accompanied with scarring. "Moreover, manipulation of HF Cav1 expression/localization would not only be relevant for management of cicatricial alopecia, but FFA could also serve as a model disease for elucidating the role of Cav1 in other stem cell- and/or IP collapse-related pathologies." (PMID 34069454, 2021).
ciliopathy (1 paper, 2023). A genetic disorder of the cellular cilia or the cilia anchoring structures, the basal bodies, or of ciliary function. "It is possible that the dynamic distribution of CAV1 at the ciliary base will affect its contribution to ciliopathy-like phenotypes." (PMID 36776558, 2023).
co-infection (1 paper, 2012). "The co-infection of macrophages with Ad-Cav-1 and psHIVwtNef, on the other hand, showed a dramatic reduction of intracellular cholesterol inclusions when compared to psHIVwtNef only infected cells." (PMID 23067370, 2012). "ADnefmut HIV infection did not affect the expression of ABCA-1 with either Ad-Cav-1 or Ad-GFP co-infection." (PMID 23067370, 2012). "Likewise, VSV-G pseudotyped HIV (psHIVwtNef) infection down-regulated ABCA-1 expression in MDMs, and co-infection of MDMs with psHIVwtNef and Ad-Cav-1 did not restore the reduced ABCA-1 levels." (PMID 23067370, 2012).
cryptorchidism (1 paper, 2024). The failure of one or both testes of a male fetus to descend from the abdomen into the scrotum during the late part of pregnancy. "Target proteins were differentially expressed in testis and cryptorchidism, and the expression tendency and expression levels was similar to that of mRNA of CAV1." (PMID 38254351, 2024). "This research will be helpful for further understanding the regulatory mechanism of CAV1 in testicular spermatogenesis and the occurrence of cryptorchidism." (PMID 38254351, 2024). "In this paper, we attempt to investigate whether CAV1 may further influence a range of male reproductive events in the yak, such as spermatogenesis, infertility and cryptorchidism, by modulating the expression of TJ-related proteins in the SCs and the integrality of BTB." (PMID 38254351, 2024). "Therefore, we hypothesize that CAV1 may play a regulatory role in tight junctions and BTB in Yaks Sertoli cells, thereby influencing the development of cryptorchidism." (PMID 38254351, 2024).
cystic tumor (1 paper, 2021). "Notably, both Cav-1 expression levels and the VM-forming ability were positively correlated with the presence of cystic tumor (P=0.000 and P=0.028, respectively), WHO grades (P=0.000 for both), and survival at 16-month interval (P=0.007 and P=0.002, respectively) using multivariate analyses." (PMID 34287575, 2021).
demyelination (1 paper, 2022). "The findings that aberrant vascular-OPC association and demyelination were remarkably attenuated by AAV-Tie1-Cav-1 suggest that the function of Cav-1 linking endothelial damage and ischemic demyelination may be cell-autonomous in endothelial cells." (PMID 36357389, 2022).
developmental delays (1 paper, 2025). "The high Caveolin-1 levels observed in yotari lungs may signal disrupted cytoskeletal dynamics or morphogen gradient interpretation, potentially contributing to structural abnormalities or developmental delays." (PMID 41010338, 2025).
diastolic heart failure (1 paper, 2022). Heart failure caused by abnormal myocardial relaxation during diastole leading to defective cardiac filling. "Genetic disruption of caveolin-1 in mice induces a severe biventricular hypertrophy with systolic and diastolic heart failure." (PMID 35872910, 2022).
dilated cardiomyopathy (1 paper, 2021). Cardiomyopathy which is characterized by dilation and contractile dysfunction of the left and right ventricles. "CAV1−/− mice are viable, but they develop dilated cardiomyopathy and PH, which are attenuated by caveolin-1 re-expression." (PMID 34698188, 2021).
dysplasia (1 paper, 2014). A usually neoplastic transformation of the cell, associated with altered architectural tissue patterns. "Both CAV1 methylation frequency and normalized methylation value (NMV) were significantly higher in Barrett’s metaplasia (BE), low-grade and high-grade dysplasia occurring in BE (D), EAC, and ESCC than in NE (all p < 0.01, respectively)." (PMID 24885118, 2014).
embryonic carcinoma (1 paper, 2012). "This association of Cav-1 with claudin-low cells supports the findings of Bailey and Liu who observed that induction of EMT in embryonic carcinoma cells or murine mammary epithelial cells was associated with elevated Cav-1 expression." (PMID 22356861, 2012).
endometrial adenocarcinoma (1 paper, 2015). "Taken together, these results implicate enhanced CAV1 expression observed in endometrial adenocarcinomas and ECC lines in promoting traits associated with a more malignant and aggressive/invasive cancer phenotype." (PMID 26054531, 2015). "Samples from normal endometrial tissues and endometrial adenocarcinomas were processed for detection of CAV1 by immunohistochemistry." (PMID 26054531, 2015). "Hence, the tumor promoting agent 4β − TPA augmented CAV1 expression in human endometrial adenocarcinoma cells." (PMID 26054531, 2015). "Quantification and comparison of CAV1 expression in normal and pathological epithelium showed that CAV1 levels were significantly elevated in pre-cancerous stages of hyperplasia, as well as G1, G2 and G3 stages of endometrial adenocarcinoma when compared to NPE." (PMID 26054531, 2015).
endometrial tumor (1 paper, 2015). "Here, we first determined by immunohistochemistry CAV1 protein levels in normal proliferative human endometrium and endometrial tumor samples." (PMID 26054531, 2015). "Immunohistochemical analysis of endometrial epithelia revealed that substantially higher levels of CAV1 were present in endometrial tumors than the normal proliferative epithelium." (PMID 26054531, 2015).
energy metabolism disorder (1 paper, 2021). "The protective effects of QSYQ are probably attributable to its ability to protect energy metabolism disorder, Caveolin-1/Src activation and inflammation, highlighting the advantage of QSYQ as a multitarget medicine." (PMID 35095486, 2021).
eosinophilia (1 paper, 2013). "The decrease in eosinophilia and overall cytokine level in aged mice both WT and Cav1-/- mice was consistent with 2 of 3 previous studies using similar allergen challenge protocols." (PMID 24138138, 2013).
epidemic keratoconjunctivitis (1 paper, 2023). Keratoconjunctivitis resulting from infection by adenoviruses. "For example, the epidemic keratoconjunctivitis (EKC) agent HAdV-37 enters human corneal epithelial cells via clathrin-dependent endocytosis but enters human keratocytes through caveolae in a caveolin 1–dependent manner." (PMID 36918926, 2023).
epithelioid melanomas (1 paper, 2025). "This suggests that CAV1 loss may be associated with less aggressive or more differentiated tumors, whereas its induction is characteristic of aggressive phenotypes, such as epithelioid melanoma." (PMID 41374987, 2025). "Taken together, CAV1 expression is downregulated in RB, mixoid melanoma, and spindle melanoma, but upregulated in epithelioid melanoma, suggesting divergent roles for this protein across ocular tumor subtypes." (PMID 41374987, 2025). "This supports our finding of CAV1 upregulation in epithelioid melanoma, as the increased caveolae in UM imply functional Cav-1 involvement in tumor progression." (PMID 41374987, 2025). "CAV1 protein was downregulated in RB, spindle melanoma, and myxoid melanoma, but upregulated in epithelioid melanoma compared with normal ocular tissue." (PMID 41374987, 2025). "CAV1 increased in epithelioid melanoma and declined in other subtypes." (PMID 41374987, 2025). "In contrast, epithelioid melanoma showed an evident upregulation of CAV1." (PMID 41374987, 2025).
experimental autoimmune encephalomyelitis (1 paper, 2025). An autoimmune demyelinating disease of the central nervous system that is produced experimentally in animals by the injection of homogenized brain or spinal cord in Freund's adjuvant. "Cav-1 is upregulated in neuroinflammatory diseases in association with greater T cell infiltration of the CNS, including in experimental autoimmune encephalomyelitis (EAE)." (PMID 40063988, 2025). "Consistent with our in vitro data, genetic ablation of Caveolin-1 reduces infiltration of CXCR3+ CD4+ T cells into the CNS in experimental autoimmune encephalomyelitis." (PMID 40063988, 2025).
folate deficiency (1 paper, 2017). A nutritional condition produced by a deficiency of FOLIC ACID in the diet. "Previous studies demonstrated that folate deficiency affected the gene expression of Esr1, Cav1, and Elavl1." (PMID 28445960, 2017). "To investigate the effect of folate deficiency on the methylation status of the ESR1, CAV1 and ELAVL1 promoters, we selected 20 semen samples with low ( < 25th percentile) and high (> 75th percentile) folate concentrations." (PMID 28445960, 2017). "In addition, folate deficiency can evidently reduce the gene expression levels of ESR1, CAV1 and ELAVL1, which are critical to spermatogenesis." (PMID 28445960, 2017).
gastrointestinal carcinoma (1 paper, 2020). "Consistent with METHY analysis, a pan-gastrointestinal carcinoma cluster with COAD/READ-STAD was gathered in C2, which had high level of CDH1, CLDN7 and TYRO3, and a low level of CAV1." (PMID 32874774, 2020).
gastrointestinal stromal tumor (1 paper, 2011). "Accordingly, the analysis of CAV1 in Gastrointestinal stromal tumors (GISTs) suggested that this protein may also act as a tumor suppressor." (PMID 21471610, 2011).
glomerulosclerosis (1 paper, 2021). A hardening of the kidney glomerulus caused by scarring of the blood vessels. "Fasudil, a Rock inhibitor, blocks the VEGF/Src/Cav-1/signaling pathway to alleviate renal inflammation, glomerulosclerosis, and proteinuria in diabetic mice." (PMID 34955837, 2021). "Another study found that CAV1 knockout in mesangial cells of diabetic mice upregulates the protein expression of follistatin, which neutralizes and inhibits activin, ultimately decreasing proteinuria, glomerular sclerosis, and extracellular matrix accumulation." (PMID 34955837, 2021). "MβCD and filipin can destroy the structure of caveolae and reduce Cav-1 phosphorylation and downstream signaling pathways, such as the Cav-1/RhoA and Scr/Cav-1/EGFR/Akt signaling pathways, resulting in the prevention of fibronectin and collagen I production and alleviation of glomerulosclerosis." (PMID 34955837, 2021).
hemangioma (1 paper, 2013). A benign vascular lesion characterized by the formation of capillary-sized or cavernous vascular channels. "Caveolin-1 remains overexpressed in the endothelial cells of the capillary tufts at the edge of the hemangioma but is reduced in the sclerosed hyaluronic lesion." (PMID 23714181, 2013). "High expression of caveolin-1 was observed in the endothelial cells of the hemangioma." (PMID 23714181, 2013).
Hematochezia (1 paper, 2025). The passage of fresh (red) blood per anus, usually in or with stools. "In addition, intestinal analysis showed that CAV1 deficiency reversed the DSS-induced shortened colon length and hematochezia." (PMID 40877233, 2025).
hemorrhagic stroke (1 paper, 2024). A stroke caused by a bleed on the brain. "In Cav-1 knockout mice, there is a reduction in heme oxygenase-1 (HO-1), macrophage inflammatory protein 2, MMP-9, and COX-2 during hemorrhagic stroke, leading to decreased immune cell infiltration and mitigated hemin-induced neuronal toxicity, ultimately improving brain damage." (PMID 38922036, 2024).
hidradenitis suppurativa (1 paper, 2025). A chronic suppurative and cicatricial disease of the apocrine glands occurring chiefly in the axillae in women and in the groin and anal regions in men. "Similarly, high expression of CAV1 is typical in hidradenitis suppurativa." (PMID 41316800, 2025).
Hodgkins lymphoma (1 paper, 2016). A heterogeneous group of malignant lymphoid neoplasms of B-cell origin characterized histologically by the presence of Hodgkin and Reed-Sternberg (HRS) cells in the vast majority of cases.
human papilloma virus infection (1 paper, 2021). An infectious process caused by a human papillomavirus. "In contrast, less differentiated p16-positive tumor epithelia (indicative for human papilloma virus infection) were characterized by significantly decreased CAV1 levels." (PMID 33868995, 2021).
hyperaldosteronism (1 paper, 2016). Overproduction of aldosterone by the adrenal glands, which may lead to hypokalemia and/or hypernatremia. "Thus, even though compound 8 itself may not be the ideal drug candidateto progress for treatment of hyperaldosteronism, there are a number of sites outsidethe dihydropyridine-binding site where CaV1.2 and CaV1.3differ sufficiently to suggest that selective blockade is achievable." (PMID 27098837, 2016).
hyperhomocysteinemia (1 paper, 2008). A serious metabolic condition caused by mutations in the MTHFR gene, medications, or nutritional deficiency. "Further, in another recent report it has been indicated that hyperhomocysteinemia induce impairment of NO production through the modulation of Cav-1 expression associated with a loss of eNOS in caveolae." (PMID 18691432, 2008).
hyperreactivity (1 paper, 2017). "Thus, cav-1/caveolae shall be considered in settings such as bronchial hyperreactivity in common airway diseases and might provide an opportunity for modulation of the constrictor response." (PMID 28555112, 2017).
hypogonadism (1 paper, 2022). A disorder characterized by decreased function of the gonads. "In addition, the following tests are suggested in serum: PHI, circulating prostate cells, caveolin-1, testosterone in men with hypogonadism, and a 3-microRNA score." (PMID 35629399, 2022).
IgA nephropathy (1 paper, 2021). "We assessed Cav-1 expression in active antibody-mediated rejection (10 cases), mixed c-ABMR and TCMR (1 case), and mixed c-ABMR (confirmed by electron microscopy) and IgA nephropathy (4 cases)." (PMID 34680435, 2021).